PRKCB (protein kinase C beta)
Diseases named in the same sentence as PRKCB in open-access papers (continued):
Sharing a sentence is not in itself a finding about the gene and the disease.
nephrolithiasis (1 paper, 2021). The presence of a calculus in the pelvis of the kidney; this is most often composed of mineral salts and proteins. "Genes in this crosstalk include those previously reported to be of functional relevance to nephrolithiasis, such as protein kinase C (PRKCA, PRKCB, and PRKCZ), markers (CD40 and TLR3), and autophagy (MTOR and SQSTM1), thus validating our genetic prioritization at the gene and pathway level." (PMID 34489936, 2021).
nicotine addiction (1 paper, 2022). "In the network of genes annotated to the cocaine pathway (also in the nicotine addiction pathway), ADCY5, DRD1, DRD2, PPP1R1B, and protein kinase C β (PRKCB) were over-expressed in Control nursed males relative to all pig groups with exception of Control weaned females." (PMID 35627199, 2022).
nonalcoholic steatohepatitis (1 paper, 2017). "Our recent demonstration that an HFHC diet induces hepatic protein kinase C beta (PKCβ) expression, whereas PKCβ deficiency sensitizes mice to hepatic cholesterol accumulation, suggests that PKCβ has the potential to modulate inflammation, nonalcoholic steatohepatitis (NASH), and HCC." (PMID 29088742, 2017).
osteoporosis (1 paper, 2024). A condition of reduced bone mass, with decreased cortical thickness and a decrease in the number and size of the trabeculae of cancellous bone (but normal chemical composition), resulting in increased fracture incidence. "The essential genes PRKCB, GSDMD, ARMCX3, and CASP3 affected periodontitis and osteoporosis by involving the MAPK signaling pathway and the neutrophil extracellular trap formation." (PMID 38511766, 2024).
partial epilepsies (1 paper, 2019). "PRKCB is a candidate gene for partial epilepsies and possibly involved in microRNA dysregulation in patients with mesial temporal lobe epilepsy." (PMID 31653223, 2019).
renal carcinoma (1 paper, 2024). A carcinoma arising from the epithelium of the renal parenchyma or the renal pelvis. "GO and KEGG pathway analyses indicated that Resibufogenin inhibited renal cancer cells through the vascular smooth muscle contraction signalling pathway and EGFR tyrosine kinase inhibitor resistance signaling pathway, and MAPK1, PRKCB, and Resibufogenin had strong associative activities." (PMID 39765731, 2024).
sarcoma (1 paper, 2021). A usually aggressive malignant neoplasm of the soft tissue or bone. "Among them, high expression levels of SMARCC1, SRSF10, PRPF38A, JARID2, GNAI3, miR-301a-3p, miR-106b-5p, miRNA-130b-3p, miR-423-3p and LINC01296 and low expression levels of ARF3 and PRKCB were associated with shorter overall survival in sarcomas." (PMID 33653335, 2021). "However, the high expressions of ARF3 and PRKCB were significantly associated with longer overall survival (P = 0.0018 and P = 0.0162), indicating that ARF3 and PRKCB overexpression could be positive prognostic factors in sarcoma patients." (PMID 33653335, 2021).
Sepsis (1 paper, 2019). Sepsis is defined as life-threatening organ dysfunction caused by a dysregulated host response to infection. "PMA induced PRKCB, improved LPS-tolerance, and attenuated sepsis severity, predominantly in FcGRIIb−/− mice." (PMID 30889825, 2019). "Indeed, PMA administration induced spleen PRKCB at 6 h after CLP and attenuated sepsis severity, as determined by survival, renal injury, liver injury, bacterial burdens, and increased serum cytokine levels in FcGRIIb−/− mice." (PMID 30889825, 2019).
ventricular septal defect (1 paper, 2016). The presence of a defect (opening) in the septum that separates the two ventricles of the heart. "The Protein Kinase C Beta (PRKCB) is also upregulated by VPA, and recently, significant copy number variation has been found in human patients with ventricular septal defects." (PMID 28038682, 2016).
cancer (62 papers, 2007 to 2026). A tumor composed of atypical neoplastic, often pleomorphic cells that invade other tissues. "Several SNPs in different PKC isoforms (rs454006, rs2242245, and rs8103851 of PRKCG, rs11079651 in PRKCA, and rs34367566 in PRKCB) have been reported to be linked with various types of cancer." (PMID 36672978, 2023). "By studying the relationship between the activity of PKC genes and the signatures of various immune cell subpopulations, we reported that in most cancer types, the levels of PRKCB, PRKCH, and PRKCQ were positively associated with the infiltration of most immune cells." (PMID 35174160, 2021). "PRKCB is downregulated in multiple tumor tissues and is believed to play a unique role in cancer-related processes." (PMID 41262895, 2025). "PRKCB is involved in cancer-related pathways and immune cell receptor signaling pathways, such as B cell receptor signaling, T cell receptor signaling, and VEGF signaling, and is associated with immune cell infiltration in NSCLC." (PMID 41262895, 2025). "Based on the drug information, 29 sex-biased mRNAs were drug-targeted genes and six (CD38, PGR, ESR1, GABRP, F3, PRKCB) of them were targeted by cancer therapeutic drugs." (PMID 39175079, 2024). "Gene set enrichment analysis (GSEA) and tumor immune estimation resource (TIMER) tumor immune correlations showed that PRKCB is involved in the cancer‐related Kyoto Encyclopedia of Genes and Genomes pathway and is involved in immune infiltration." (PMID 35567329, 2022). "It has been reported that these genes were closely associated with cancer progression, including ENO1, PRKCB, ENO2, and PDK1." (PMID 35504868, 2022). "The results show that PRKCB is indeed involved in cancer‐related pathways and immune cell receptor signaling pathways." (PMID 35567329, 2022). "Taken together, these results suggested that PRKCB was indeed involved in the cancer‐related KEGG pathway." (PMID 35567329, 2022). "The activation of PRKCB accelerated the mitochondrial accumulation and the redox response to enhance signaling transduction pathways in cancer cells." (PMID 34631528, 2021). "We found that PRKCB, PRKCH, and PRKCQ levels were directly associated with HLAs scores in almost most cancers, especially for PRKCB, whose elevated expression moderately to strongly controlled the HLA level in 28 cancer types (R ˃ 0.3)." (PMID 35174160, 2021). "PRKCB overexpression was found to attenuate autophagy, an important pathway in diseases such as neurodegeneration and cancer." (PMID 33255928, 2020). "For example, AGTR1, GRIN2A, ITPKB, and SLC8A3 were repressed by hypermethylation in six cancer types, and ADCY4, ADCY8, BST1, and PRKCB were inhibited by hypermethylation in five cancer types." (PMID 28060724, 2017). "To investigate this further we examined the relative expression of PRKCB in normal distant tissue and compared it to cancer tissue, normal tissue and benign tissue." (PMID 26989024, 2016). "We thus note a theme already observed here, in that in addition to their involvement in ASDs, both CACNA1s and PRKCB are reported to be involved in both cancer development and metabolism-related issues." (PMID 27055244, 2016). "Moreover, because gene methylation modifications usually occur in the early stage of cancers, the methylation change of the PRKCB gene may occur in the early stage of LUAD, which may have certain value for the early diagnosis of LUAD patients." (PMID 35567329, 2022). "Analysis of single-cell transcriptomic data from the TISCH2 database (GSE117570) revealed that PRKCB is highly expressed in B cells, CD8+ effector T cells (CD8 Teff), and NK cells, while its expression is low in malignant tumor cells." (PMID 41262895, 2025). "Variations in both PRKCB and PRKCQ play significant roles in certain cancers and are considered excellent predictive biomarkers for these diseases." (PMID 39238930, 2024).
cancer (continued). "Overall, the candidate gene set was significantly enriched for known cancer census genes (e.g. SGK1, MECOM, PRKCB) and known transcription co/factors (e.g. CACNA2D3, BMP4)." (PMID 36624125, 2023). "Genes related to high expression of PRKCB were concentrated on NSCLC, pathways in cancer, B cell receptor signaling, T cell receptor signaling, VEGF signaling pathway, and so on." (PMID 35567329, 2022). "In contrast, PRKCB, PRKCH, and PRKCQ expressions were positively correlated with TLLs among most cancer types." (PMID 35174160, 2021). "Protein kinase C (PKC), including PRKCB and PRKCA, is involved in diverse cellular signalling pathways, including those involved in cancer." (PMID 33241658, 2021). "Collectively, the expression levels of PRKCI and PRKCG were elevated in most of the significantly compared cancers, while PRKCA, PRKCB, PRKCE, and PRKCQ tended to be downregulated among most cancer types." (PMID 35174160, 2021). "The most crucial finding in this study was that PKC isoenzymes are robust biomarkers for the tumor immune status, PRKCB, PRKCH, and PRKCQ as stimulators, while PRKCI and PRKCZ as inhibitors in most cancers." (PMID 35174160, 2021). "Our comprehensive gene expression analysis of all PKC isoforms revealed that three of the nine PKC coding genes (PRKCB, PRKCD and PRKCE) showed a down-regulation greater than two in the cancer tissue, while only one of the genes (PRKCG) was up-regulated." (PMID 26989024, 2016). "Six overexpressed oncogenes including BCL2, NOTCH1, SOX4, and CTNNB1 and 10 downregulated tumor suppressor genes including PRKCB, IRF1, CYLD, and TGFB1 were identified as the targets of the DE miRNAs, which may promote cancer development." (PMID 34336826, 2021). "The genes that were shared by three different cancers (i.e., FGFR3, EPAS1, SRC, and FOXD3) are shown in coral, and the genes that were shared by two types of cancers (i.e., PPARG, FOXO1, CDK4, NKX3-1, PIK3R1, PRKCB and EDNRB) are shown in light pink." (PMID 28178311, 2017). "To validate these results, based on the 340 epigenetically silenced genes in at least five cancer types, we drew a protein-protein interaction network and found some genes with higher degrees of interaction, such as ADCY4, ADCY8, and PRKCB.." (PMID 28060724, 2017). "Overall the top three enriched targets in the cluster can be classified into immunomodulation, which are PTPN2, protein kinase C beta type (PKC-β), protein kinase C eta type (PKC-η), and protein kinase C gamma type (PKC-γ), cancer, namely, TOPO1, and glucose homeostasis, such as SGLT2." (PMID 26989424, 2016). "Although the roles of another four genes (SCUBE2, PRKCB, IKZF1, and MAP4K1) in NPC were not known, their functions were reported in other cancer types." (PMID 33403044, 2021).
tumor (62 papers, 2007 to 2025). "We further explored the molecular basis of miR-4664-3p regulation of the tumor immune microenvironment and found that its target gene PRKCB was significantly downregulated in NSCLC, and was negatively correlated with miR-4664-3p expression." (PMID 41262895, 2025). "miR-4664-3p promotes tumor progression by inhibiting PRKCB, which affects the infiltration and activity of CD8+ T cells." (PMID 41262895, 2025). "ROC analysis showed that the AUC of PRKCB in distinguishing NSCLC tumor tissues from normal tissues was 0.854 (95% CI: 0.826–0.882), demonstrating good diagnostic performance." (PMID 41262895, 2025). "qRT-PCR analysis revealed that miR-4664-3p inhibition significantly upregulated PRKCB mRNA expression in tumor tissues." (PMID 41262895, 2025). "In consistence with this, the expression of ENO1 and PDK1 were elevated and PRKCB was decreased in matched LUAD tumor tissues compared with normal tissues." (PMID 35504868, 2022). "At the same time, PRKCB was reduced in tumor tissues and downregulated PRKCB expression was indicative of a low survival possibility in LUAD patients." (PMID 35504868, 2022). "Both in vivo and in vitro, PRKCB was shown to play a role in the maintenance of EwS tumor size and cell survival." (PMID 34604225, 2021). "Recurrent fusions of PRKCB and PRKCD to membrane-associated proteins were identified in BFHs, one of the most common neoplasms in the skin." (PMID 33617877, 2021). "Combinatorial treatment with statin and protein kinase C-beta inhibitor was shown to display enhanced anti-tumor efficacy in cultured HCC cells and in a mouse model of HCC." (PMID 32162652, 2020). "An early experimental study showed that combinatorial treatment with statin and protein kinase C-beta inhibitor displayed enhanced anti-tumor efficacy in cultured HCC cells and in a mouse model of HCC." (PMID 32272891, 2020). "Both mechanistic features and recent correlative findings suggest a potential role for protein kinase C-beta (PKC-β) in tumor pathogenesis, particularly in B-cell malignancies." (PMID 17313671, 2007). "The authors take a statistical and bioinformatics approach to rexamine the role for protein kinase C-beta (PKC-b) in tumor pathogenesis related to B-cell malignancies." (PMID 17313671, 2007). "Taken together, these results suggest that miR-4664-3p may promote immune evasion and tumor progression by suppressing PRKCB and weakening CD8+ T cell activity." (PMID 41262895, 2025). "The expression of PRKCB is accompanied by a large number of immune cell infiltrations, which means that PRKCB may play an important role in the tumor microenvironment of LUAD by regulating the tumor infiltration of immune cells." (PMID 35567329, 2022). "Furthermore, knockout of PRKCB in the mouse model reduced the volume and the collagen amounts in the tumor." (PMID 34604225, 2021). "The PRKCB gene is a member of the protein kinase C family of serine/threonine kinases that have functions in signal transduction pathways involving hormone release, mitogenesis, tumor progression, and regulation of uterine smooth muscle contractions." (PMID 31766405, 2019). "However, in the current study, higher methylation level of PRKCB promoter was observed in tumor tissues than adjacent normal tissues." (PMID 28422739, 2017). "SFRP1, SFRP2 and PRKCB methylation levels could discriminate NSCLC tissues from adjacent non-tumor samples." (PMID 28422739, 2017). "Conversely, the inhibition of miR-4664-3p increased PRKCB expression, boosted CD8 + T cell activity, strengthened anti-tumor immunity, and suppressed tumor growth." (PMID 41262895, 2025). "These ER+ tumours also demonstrate metabolic optimization through regulators such as HK3, LDHAL6A, ADH6, and PRKCB, which collectively shift metabolism toward greater efficiency." (PMID 41007296, 2025).
tumor (continued). "In our study, functional enrichment analysis of 2160 proteins commonly expressed in 13qCLL/MBL tumor cells identified critical phosphoproteins involved in BCR signaling, immune response regulation, and cell cycle regulation, such as BTK, PRKCB, STAT1, and SYK." (PMID 40129242, 2025). "Two of the 16 dmCpGs were in genes that were significantly down-regulated in Australian tumour samples (Bonferroni p < 0.01; GSTM2 and PRKCB)." (PMID 39095452, 2024). "Of our 16 LASSO-selected dmCpGs, two were present in genes, PRKCB and GSTM2, that were significantly down-regulated in tumour compared with benign samples (Bonferroni p-value < 0.01)." (PMID 39095452, 2024). "Thirteen kinases differentially expressed at the protein level in GAC tumor tissues with lymph node metastasis were plotted in a heatmap, including known drug targets JAK1, MAP3K4, and PRKCB, among others." (PMID 36520032, 2023). "CLDN7, PRKCB, EEF2 and TFRC protein levels were all found at higher levels in high LN yield tumours (q = 0.0283)." (PMID 35043009, 2022). "Matched to other genes, PRKCA, PRKCB, and PRKCE were more involved in many normal tissue mRNA profiles than tumor ones." (PMID 35174160, 2021). "The percentage of methylated reference (PMR) levels of SFRP1, SFRP2, PRKCB and WIF1 in 111 NSCLC tumor tissues and 111 paired adjacent tissues were quantified by SYBR green-based quantitative methylation-specific PCR (qMSP)." (PMID 28422739, 2017). "An enhanced macrophage infiltration into EwS tumors following the transfer of PRKCB and CCND1 transcripts could promote tumor growth, potentially by increasing the density of macrophages in tumors to amplify the immunosuppressive effects of their proinflammatory cytokines triggered by EZH2 and DKK2." (PMID 34604225, 2021).
infection (8 papers, 2010 to 2024). The state of being infected such as from the introduction of a foreign agent such as serum, vaccine, antigenic substance or organism. "The significant reduction of PRKCB in the FcGRIIb−/− macrophage over wild-type cell possibly induced the more severe LPS-exhaustion and increased the infection susceptibility in FcGRIIb−/− mice." (PMID 30889825, 2019). "Interestingly, only the immune-regulatory CBLB gene and the multifunctional PRKCB gene were downregulated by infection." (PMID 23425254, 2013). "A recent study involving proteomics of human tissue showed the effect of inflammation post-infection on the basal ganglia and the brain stem and suggested changes in trafficking in AMPA receptors via inflammation, along with increased abundance of protein kinases PRKCG, PRKCB, and CAMK2A/B." (PMID 38002279, 2023).
kidney disease (6 papers, 2015 to 2025). "In this work, we discovered 20 top eccDNA hub genes in which NCAM1, NFATC1, PRKCB, LEF1, PRKAG2, and GRM8 were strongly linked to a variety of kidney disorders." (PMID 36967395, 2023).
retinopathy (4 papers, 2009 to 2025). "Similarly enhanced activation of the protein kinase C beta pathway is present and an orally active, PKC beta inhibitor reduces retinopathy progression." (PMID 20111736, 2009).
adenocarcinoma (2 papers, 2019 to 2022). A common cancer characterized by the presence of malignant glandular cells. "Studies have found that PRKCB promoters are hypermethylated in a variety of adenocarcinomas." (PMID 35567329, 2022).
psychiatric disorder (1 paper, 2024). A disorder characterized by behavioral and/or psychological abnormalities, often accompanied by physical symptoms. "We identified dysregulations in four PKC genes—PRKCA, PRKCB, PRKCH, and PRKCI—known for their roles in mood regulation and stress response, crucial for neurodevelopment and linked to psychiatric disorders." (PMID 39238930, 2024).
PRKCB also shares sentences with these, for which no sentence is quoted: diabetic retinopathy (11 papers); heart failure (10); type 2 diabetes (6); diffuse large B-cell lymphoma (5); ischemia (5); leukemia (5); colorectal cancer (4); Hypertension (4); Nephropathy (4); acute myeloid leukemia (3); glomerulosclerosis (3); lung squamous cell carcinoma (3); Myocardial fibrosis (3); myocardial ischemia (3); non-small cell lung carcinoma (3); pancreatic cancer (3); aorta (2); atrial fibrillation (2); bladder cancer (2); breast tumor (2); cardiac disease (2); cardiovascular diseases (2); diabetic cardiomyopathy (2); diabetic neuropathy (2); fibrosis (2); Hepatic steatosis (2); influenza (2); Meniere disease (2); metabolic disease (2); metabolic syndrome (2).
A further 91 diseases each share a sentence with PRKCB in 2 papers or fewer.